OGN (osteoglycin)
Description:
Induces bone formation in conjunction with TGF-beta-1 or TGF-beta-2.
Synonyms: OIF; SLRR3A; mimecan; OG
Tractability: Antibody: its Gene Ontology location is reachable by antibodies, with high confidence; UniProt places it where antibodies can reach, with medium confidence; UniProt predicts a signal peptide or a membrane-spanning region. PROTAC: ubiquitination databases record sites on it; its protein half-life has been measured.
Gene: Protein-coding gene on chromosome 9 (92,383,268 to 92,406,734, reverse strand). Ensembl gene ENSG00000106809.
Subcellular location: Secreted, extracellular space, extracellular matrix
Subcellular location (Human Protein Atlas): Endoplasmic reticulum; Predicted to be secreted
Pathways (Reactome):
Disease: Defective B4GALT1 causes B4GALT1-CDG (CDG-2d); Defective CHST6 causes MCDC1; Defective ST3GAL3 causes MCT12 and EIEE15
Metabolism: Keratan sulfate biosynthesis; Keratan sulfate degradation
Gene Ontology:
Molecular function: protein binding; extracellular matrix structural constituent conferring compression resistance
Biological process: articular cartilage development; bone development; negative regulation of smooth muscle cell proliferation
Cellular component: endoplasmic reticulum; extracellular exosome; extracellular matrix; extracellular region; extracellular vesicle; gel phase of interstitial matrix; Golgi lumen; lysosomal lumen
Genetic constraint (gnomAD): Loss-of-function variants: 6 observed, 13.35 expected, observed/expected ratio (o/e) 0.45, 90% interval 0.25 to 0.89. The upper end of that interval is the gene's LOEUF score, 0.89, which puts it in group 3 of 6, group 1 being the genes least tolerant of losing a copy. Missense variants: 153 observed, 208.89 expected, observed/expected ratio (o/e) 0.73, 90% interval 0.64 to 0.84. Synonymous variants: 71 observed, 78.17 expected, observed/expected ratio (o/e) 0.91, 90% interval 0.75 to 1.11.
Homologues: Orthologues: chimpanzee OGN (99% identical), macaque OGN (98% identical), dog OGN (91% identical), pig OGN (89% identical), rabbit OGN (88% identical), mouse Ogn (85% identical), guinea pig OGN (84% identical), rat Ogn (81% identical), tropical clawed frog ogn (57% identical), zebrafish ogna (50% identical), zebrafish ognb (46% identical). Paralogues in human: EPYC (40% identical), LINGO3 (26% identical), LUM (24% identical), ECM2 (21% identical), FMOD (21% identical), OMD (21% identical), PRELP (21% identical), KERA (20% identical), LINGO4 (19% identical), OMG (15% identical).
Diseases named in the same sentence as OGN in open-access papers:
OGN is named in the same sentence as 86 diseases in open-access papers, as found by Europe PMC text mining. Sharing a sentence is not in itself a finding about the gene and the disease. The quoted sentences say what the papers report.
colorectal cancer (17 papers, 2018 to 2025). A primary or metastatic malignant neoplasm that affects the colon or rectum. "OGN expression is associated with increased survival and decreased recurrence of colorectal cancer." (PMID 40051609, 2025). "In colorectal cancer, OGN reversed epithelial to mesenchymal transition (EMT) and invasive ability by the EGFR/Akt signaling." (PMID 38402185, 2024). "In colorectal cancer, OGN upregulation has been found to induce EGFR endocytosis and inhibit EMT through the EGFR/Akt pathway." (PMID 36980828, 2023). "OGN has been reported in colorectal cancer and cervical cancer to affect the EMT of cancer cells, which is consistent with our research results." (PMID 37352032, 2023). "The effect of OGN on inflammatory cell infiltration in colorectal cancer is better explained in this paper, demonstrating its function in tumor microenvironment regulation." (PMID 36421687, 2022). "In most cases, the expression of OGN is decreased in tumor tissues compared with normal tissues, as shown in squamous cervical cancer, gastric cancer, colorectal cancer, vaginal cancer, invasive ductal breast carcinoma, laryngeal carcinoma, and thyroid tumors." (PMID 36421687, 2022). "OGN has the ability to reduce proliferation and invasion of colorectal cancer cells by binding EGFR and promoting its internalization, resulting in the impairment of pro-mitotic signaling and EMT driven by the EGFR/AKT/Zeb-1 axis." (PMID 35454809, 2022). "In colorectal cancer cells, increased OGN expression hindered the activation of the transcriptional gene hypoxia-inducible factor-1 (HIF-1), which then inhibited the synthesis of vascular endothelial growth factor (VEGF), reducing T-cell tumor invasion." (PMID 36421687, 2022). "In colorectal cancer, OGN expression reduces cell proliferation, inhibits invasion and limits cancer progression." (PMID 32545553, 2020). "OGN, a small leucine-rich proteoglycan family member, was found down-regulated in cervical cancer, gastric cancer, and colorectal cancer." (PMID 33015704, 2020). "There are two main complementary findings highlighted in this study: 1) a positive association between OGN and improved survival in primary CRC tumors; and 2) reduced activation of EGFR/AKT/Zeb-1 in colorectal cancer cells when OGN over-expressed." (PMID 29499765, 2018). "OGN plays a restrictive role in colorectal cancer progression by reduced activation of EGFR/AKT/Zeb-1." (PMID 29499765, 2018). "In colorectal cancer, OGN reversed EMT and invasive abilities through the EGFR/Akt pathway." (PMID 38402185, 2024). "OGN plays an oncogenic role in the progression of both breast cancer and colorectal cancer." (PMID 35620271, 2022). "Similarly, the small leucine-rich proteoglycan osteoglycin (OGN) was recently reported to be down-regulated in colorectal cancer patients with a worse prognosis." (PMID 35454809, 2022). "Furthermore, patients with high OGN expression had a significantly longer survival in colorectal cancer, and a high blood OGN level was consistently related to fewer recurrences." (PMID 36421687, 2022). "A previous proteomic study found that, whereas all adenoma and cancer tissues did not express OGN, all normal mucosa did, indicating that OGN deficiency is linked to the development of colorectal cancer." (PMID 36421687, 2022). "Although many studies identified that the expression levels of OGN would alter in cancers, such as gastric cancer, colorectal cancer, and invasive ductal breast carcinoma, functional data about how OGN participating in cancer pathology are not enough, and further studies are needed." (PMID 32300359, 2020). "Furthermore, we observed that ECRG4 expression was positively correlated with OGN, which is a tumor suppressor in colorectal cancer and breast cancer." (PMID 32922434, 2020).
colorectal cancer (continued). "The CCK-8 assays were applied to examine whether OGN expression affected colorectal cancer cells proliferation and viability in vitro." (PMID 29499765, 2018). "OGN can reverse EMT by suppressing the EGFR/AKT/Zeb-1 axis, which is an indicator of increased survival and decreased cancer recurrence in colorectal cancer." (PMID 36421687, 2022). "Regarding to the observations above that OGN suppressed EGFR activity in HT29 and SW620 colorectal cancer cells, we aimed to identify which downstream pathways of EGFR will be inhibited after OGN over-expression." (PMID 29499765, 2018). "Many types of cancers are devoid of the small leucine-rich proteoglycans: osteoglycin (OGN), but its role in tumorigenesis is poorly studied especially in colorectal cancers (CRC)." (PMID 29499765, 2018). "Despite several studies demonstrating consistent OGN decrease in cancers, functional data on how OGN is involved in cancer pathology, especially colorectal cancers are lacking, and further research is needed." (PMID 29499765, 2018).
breast carcinoma (13 papers, 2017 to 2025). "Low OGN expression was significantly associated with poor RFS in Basal-subtype breast cancer." (PMID 33644115, 2021). "In another study in breast cancer, OGN levels were significantly reduced in breast cancer tissue; overexpression of OGN significantly inhibited cell proliferation, migration, and invasion and reversed EMT phenotypic changes." (PMID 40051609, 2025). "Within breast carcinoma, OGN suppresses the capacity of tumor cells to proliferate and invade through the PI3K/Akt/mTOR signaling." (PMID 38402185, 2024). "OGN can inhibit breast cancer cell proliferative and invasive properties via mediating PI3K/Akt/mTOR signaling pathway." (PMID 35837663, 2022). "OGN can reverse EMT through the PI3K/Akt/mTOR pathway in breast cancer, and reduce the expression of ZEB-1 through the EGFR/Akt signaling pathway in colon cancer to inhibit EMT." (PMID 35513835, 2022). "Because of its effects on the PI3K/AKT/mTOR pathway, overexpression of OGN dramatically reduces cell growth in breast cancer cells, demonstrating that OGN is a tumor suppressor in breast cancer." (PMID 36421687, 2022). "Recently, OGN was discovered to be upregulated in dormant breast cancer cells compared to proliferative cells, serving as a marker for breast cancer and a prognostic factor for breast cancer patients." (PMID 36421687, 2022). "Our results found that OGN expression was significantly different in the Basal-like subtype from other breast cancer subtypes, and its expression in Basal-like subtype was lower than that in other subtypes." (PMID 33644115, 2021). "Finally, we also detected a modulation of genes that have been identified as tumor suppressors in other cancer types, including OGN, a gene that is downregulated in the breast cancer and that functions as PI3K/AKT/mTOR suppressor." (PMID 34012923, 2021). "Osteoglycin (OGN) is a type of SLRP that has been found to be downregulated in many different cancers, including cervical cancer, breast cancer, and colon cancer." (PMID 35513835, 2022). "Overexpression of OGN significantly inhibits cell proliferation and migration/invasion and reverses EMT phenotypes in breast cancer cells through its effects on the PI3K/AKT/mTOR pathway." (PMID 36421687, 2022). "In the selected key specific DEGs for Basal-subtype breast cancer, the altered expression of SOX11, PLK1, BUB1, OGN, COL4A6, AGTR1, and ADRB2 were significantly correlated with the prognostic survival of the patients." (PMID 33644115, 2021). "Reportedly, OGN could inhibit the capacity of tumor cells to proliferate and invade through the PI3K/Akt/mTOR signaling in breast carcinoma." (PMID 38402185, 2024). "SOX11, PLK1, BUB1, OGN, COL4A6, AGTR1, and ADRB2 may be involved in the recurrence of Basal-subtype breast cancer, and to some extent the PLK1, BUB1, OGN, COL4A6, AGTR1, and ADRB2 can be used as the specific prognostic markers for Basal-subtype breast cancer." (PMID 33644115, 2021).
gastric cancer (8 papers, 2020 to 2025). A primary or metastatic malignant neoplasm involving the stomach. "A significant reduction in OGN expression was observed in gastric cancer tissues, and a decrease in OGN expression was associated with more lymph node metastasis and poor differentiation status, both indications that a cancer has advanced." (PMID 40051609, 2025). "OGN was also found to be significantly associated with poor survival in patients with gastric cancer (GC), and its expression increased as the cancer progressed, according to a functional enrichment analysis." (PMID 36421687, 2022). "Osteoglycin (OGN) showed to be decreased within multiple malignancies, such as stomach cancer, cervical squamous carcinoma, vaginal cancer, colorectal adenoma, invasive ductal breast carcinoma, and laryngeal carcinoma." (PMID 38402185, 2024). "Decreased OGN expression has been observed in a variety of different cancers, including gastric cancer, colorectal adenoma, squamous cervical and vaginal cancer, invasive ductal breast carcinoma, and laryngeal carcinoma." (PMID 32545553, 2020). "Therefore, further biological experiments in vivo and in vitro are required to confirm the functions of OGN, JAM2, RERG, OLFML2B and ADAMTS1 genes in gastric cancer in the future." (PMID 33015704, 2020).
osteoporosis (8 papers, 2017 to 2024). A condition of reduced bone mass, with decreased cortical thickness and a decrease in the number and size of the trabeculae of cancellous bone (but normal chemical composition), resulting in increased fracture incidence. "Especially COL1A1, the major organic component of bone matrix and OGN, which was found to be downregulated in senile osteoporosis, was significantly higher expressed in osteogenically treated JPCs without dexa." (PMID 36393863, 2022). "Hsa_circ_0076906 promoted osteogenesis and alleviated osteoporosis by acting as a sponge for miR-1305 and upregulating osteoglycin." (PMID 33648601, 2021). "circPRIM2 (circbase ID: hsa_circ_0076906) binds to miR-1305 to regulate the expression of OGN (osteoglycin) and alleviate osteoporosis." (PMID 34482380, 2021). "Hsa_circ_0076906 promotes osteogenesis and alleviates osteoporosis by acting as a sponge for miR-1305 and upregulating osteoglycin." (PMID 33648601, 2021). "In next steps, we will do further study on the appropriate manipulation of PPARγ2 expression by regulating OGN in senescence accelerated mouse prone/6 (SAM-P6), which is to the benefit of preventing bone loss in senile osteoporosis." (PMID 29073887, 2017). "As is indicated in our findings, up-regulation of PPARγ2 is involved in inhibiting expression of osteogenic-related marker (such as OGN) in senile osteoporosis." (PMID 29073887, 2017). "Additionally, Circ_0076906 relieves osteoporosis and promotes osteogenic differentiation through miR-1305/OGN pathway." (PMID 34266353, 2021). "OGN may plays a significant role in osteoporosis, which may also provide a potential target for therapeutic intervention of senile osteoporosis characterized by altered differentiation of BMSCs into osteoblasts and adipocytes." (PMID 29073887, 2017). "Therefore, OGN can be served as a common factor to regulate the directional differentiation of MSCs, and a novel target of therapy for senile osteoporosis." (PMID 29073887, 2017). "Therefore, the miRNA-702-5p/OGN/Runx2 signaling axis may play a role in DOP, and could be diagnostic biomarker and therapeutic target for not only DOP but also other forms of osteoporosis." (PMID 38862780, 2024). "Our results showed that the OGN serum level was an independent estimator of impaired kidney function risk in T2D patients by increasing the risk by 8% for a 1 ng/mL increase in the serum OGN regardless of other comorbidities such as CVD or osteoporosis." (PMID 34065223, 2021).
meningioma (7 papers, 2017 to 2022). A generally slow growing tumor attached to the dura mater. "Although its role in meningioma genesis is still unclear, high OGN mRNA levels with NF2 or chromosome 22 loss have been identified." (PMID 35892898, 2022). "AKT inhibitors have been shown to downregulate the expression of osteoglycin (OGN), an oncogene implicated in meningioma growth, in vitro and to stabilize meningotheliomatous meningioma growth in the lung of a patient with multiple intra- and extra-cranial tumors." (PMID 36686824, 2022). "OGN has been implicated in meningioma through effects on mTOR and NF2 signaling, but whether it may be a therapeutic target is unclear." (PMID 33622177, 2021). "We investigated the effects of OGN, a critical regulator of bone and cardiovascular development, in meningioma proliferation, its association with other known signaling pathways involved in meningioma development, and explored the treatment options for OGN-expressing meningioma cells." (PMID 28923059, 2017). "Meningiomas, in contrast, have significantly higher mRNA expression of OGN than other brain cancers and normal brains." (PMID 36421687, 2022). "Through downregulation of (neurofibromatosis type 2) NF2 and activation of mTOR/Akt signaling, OGN-overexpressing meningioma cells displayed an increased rate of cell proliferation, cell cycle activation, and colony formation when compared to control cells." (PMID 36421687, 2022). "A new study found that chrysophanol, an anthraquinone with purportedly potent antitumor effects, can block OGN’s action on meningiomas in order to achieve its antitumor effect." (PMID 36421687, 2022). "HBL-52 meningioma cells overexpressing OGN showed increased levels of activated mTOR and down-regulated NF2 protein at 48 h (p< 0.05)." (PMID 33622177, 2021). "Our findings indicated that chrysophanol inhibits OGN/mTOR signaling but induces NF2 signaling in meningioma cells." (PMID 33622177, 2021). "For example, OGN promotes meningioma cell proliferation by interacting with other drivers of tumor development, including neurofibromatosis 2 (NF2) and mammalian target of rapamycin (mTOR)." (PMID 33622177, 2021). "In summary, this present observation demonstrates the inhibitory effect of chrysophanol on malignant meningioma cells and its regulatory roles in the signaling transduction of OGN/mTOR and NF2 cascades." (PMID 33622177, 2021). "A study of human meningioma cell lines found that meningioma with over-expression of osteoglycin (OGN) exhibited higher cell proliferation, cell cycle activation and colony formation rate, activities closely associated with the PI3K/Akt/mTOR pathway." (PMID 33042832, 2020). "Our results implicate OGN as an important mitogenic factor in meningioma growth across a range of tumor subtypes." (PMID 28923059, 2017). "We performed an integrated genomic and molecular analysis to characterize the expression and function of osteoglycin (OGN) in meningiomas and explored possible therapeutic approaches for OGN-expressing meningiomas." (PMID 28923059, 2017). "OGN participates in meningioma formation in a distinct manner from previously identified genetic alterations." (PMID 28923059, 2017). "Transitional and atypical meningiomas demonstrated the highest levels of OGN mRNA while psammomatous meningiomas demonstrated the lowest (p = 0.0041)." (PMID 28923059, 2017). "In meningiomas with known treatment status, OGN mRNA expression levels in primary (74 samples) and recurrent (24 samples) tumors were comparable (data not shown)." (PMID 28923059, 2017). "AKT inhibition reduces OGN protein levels in meningioma cells, with a concomitant increase in cell death." (PMID 28923059, 2017). "OGN mRNA expression was dramatically increased in meningiomas compared to a spectrum of other brain tumors and normal brain." (PMID 28923059, 2017).